CRP (C-reactive protein)
Diseases named in the same sentence as CRP in open-access papers (continued):
Sharing a sentence is not in itself a finding about the gene and the disease.
infection (continued). "For each type of infection, ESR + CRP diagnosed 85.7% of early, 77.7% of delayed, and 73.9% of late cases." (PMID 35086474, 2022). "Laboratory investigations including a CRP level of 1.9 mg/L and ESR of 10 mm/hour, suggesting a low likelihood of infection." (PMID 35317840, 2022). "In conclusion, to investigate infection in a military scenario, we develop a WMC-MDP for multiplexed detections of CRP, PCT, and IL-6." (PMID 35144683, 2022). "- When comparing C-reactive protein (CRP), white cell count (WCC), and procalcitonin (PCT) to diagnose infection in 65 neonatal and pediatric ECMO runs, the performance of CRP was best." (PMID 35155322, 2021). "However, in the context of a proven infection, CRP/PCT kinetics may be used for patient management." (PMID 34645893, 2021). "ROC curves were performed for PCT, CRP, and WBC levels to identify infections in the IWS group, and the AUCs were calculated." (PMID 34344141, 2021). "Compared with CRP, SAA is a highly sensitive infection-mediated biomarker, especially for infections involving lung tissues." (PMID 34205852, 2021). "Inflammatory proteins, enzymes, and C-reactive protein (CRP) have been used as biomarkers in medicine to assess levels of inflammation, infection, and injury." (PMID 34307692, 2021). "Postoperative CRP and ESR levels are routinely monitored to detect postoperative inflammation and infection." (PMID 34380501, 2021). "Regarding the infection index, most patients had erythrocyte sedimentation rate (ESR), C-reactive protein (CRP), serum ferritin (SF) and interleukin-6 (IL-6) above the normal range." (PMID 33542448, 2021). "Acute-phase proteins including C-reactive protein (CRP) and procalcitonin (PCT) are early markers of infection that are frequently used to diagnose the infection." (PMID 34820395, 2021). "CRP and PCT are acute-phase inflammatory proteins and related to the severity of body systematic infection." (PMID 33638944, 2021). "In a study on patients with mild infection, abnormal laboratory results were obtained, such as increased levels of the erythrocyte sedimentation rate (ESR), C-reactive protein (CRP), D-dimer and lactate dehydrogenase (LDH)." (PMID 34812049, 2021). "There was significant heterogeneity in COX-2 expression in AD/ACLF and circulating PGE2 levels correlated positively with serum CRP, supporting increased COX-2 expression in patients with AD/ACLF with the greatest systemic inflammation or infection." (PMID 34825153, 2021). "This animal also had elevated plasma levels of two inflammatory markers, interleukin-6 (IL-6) and C-reactive protein (CRP), 2 days after infection." (PMID 34817208, 2021). "We assessed the diagnostic accuracy of Procalcitonin (PCT), C-reactive protein (CRP) and White cell count (WCC) to diagnose infection on ECMO." (PMID 35155322, 2021). "Both CRP and ESR, which are considered as specific indicators of infection, were shown to be highly elevated in the PJI group and to gradually decline postoperatively." (PMID 34536150, 2021). "C-reactive protein (CRP) and procalcitonin (PCT) are the most commonly used infection-related indicators in clinical practice, however too many influencing factors and poor sensitivity in the elderly population, limit their early diagnostic value." (PMID 34255213, 2021). "E. coli challenge significantly increased the serum concentration of CRP, DAO, and LPS (P < 0.05) compared with unchallenged birds and challenged birds fed with L. acidophilus over the whole infection period (14 d and 21 d)." (PMID 34280647, 2021). "The level of sIL-2R was positively correlated with CRP, SAA, IL-6, APACHE II, and the SOFA score in the infection group (r = 0.396, p < 0.001; r = 0.314, p < 0.008; r = 0.262, p = 0.028; r = 0.302, p = 0.011; and r = 0.348, p = 0.003, respectively)." (PMID 34745113, 2021).
infection (continued). "Among infectious diseases, PCT, CRP, ESR, SF is used as an inflammatory indicator to monitor the severity of infection, and we used these biomarkers to monitor MPP severity." (PMID 33752670, 2021). "In the present study, plasma levels of HBP were positively correlated with the levels of N%, IL-6, CRP, D-dimer, PCT, and WBC, suggesting that HBP and other candidate mediators increase in response to infection and inflammation." (PMID 34778149, 2021). "The role of biomarkers such as procalcitonin (PCT) and C-reactive protein (CRP) is already well established in infections; the PCT and CRP dosing are routinely used to confirm the presence of infection and in the follow-up during medical treatment." (PMID 33664308, 2021). "To date, there are no guidelines or controlled trials that define optimal antibiotic therapy, but there is consensus that antibiotic therapy should be discontinued when laboratory infection parameters (WBC count, CRP concentration) normalize." (PMID 34439638, 2021). "C-reactive protein (CRP) is a plasma protein that participates in the systemic response to inflammation and the synthesis of which rapidly increases within hours of an infection or tissue injuries and apoptosis." (PMID 34940253, 2021). "Prediction of relevant pathogens in BAL cases by parameters of infection: Laboratory parameters of infection (PCT, CRP and WBC count) were similar between the groups." (PMID 33572924, 2021). "C-reactive protein and the proportion of ICU isolation of the infection group were significantly higher than that of the colonization group (P < 0.05)." (PMID 34926395, 2021). "The C-reactive protein (CRP) is the acute phase protein; however it has low specificity for infections." (PMID 34324506, 2021). "Mtb-AG infection significantly upregulated the expression of inflammatory molecules S100A8, S100A9, CRP, IL23, activated NK cell marker (KLRG), and Th-2 type marker, IL10 at 1 week post infection." (PMID 34732811, 2021). "C-reactive protein (CRP) and procalcitonin (PCT) are currently used as infection biomarkers; nevertheless, they change considerably during the early neonatal period due to several non-infectious conditions." (PMID 34830040, 2021). "Traditional infection markers included white blood cell (WBC) count, neutrophil ratio, lymphocyte ratio, C-reactive protein (CRP) and procalcitonin." (PMID 34737270, 2021). "Infection markers impact RV and LV differently, the former being influenced by HRCT and HI, and the latter by CRP." (PMID 34829406, 2021). "C-reactive protein (CRP), a sensitive indicator of inflammation rapidly produced by the liver after tissue injury or infection, is one of the most widely used markers in clinical practice." (PMID 33402185, 2021). "We should monitor CRP ≥ 8 mg/L, C3 ≤ 0.55 g/L and ALC ≤ 1.5 × 109/L to avoid developing severe infection." (PMID 34336733, 2021). "Inflammatory markers, including CRP and ESR, were higher in patients with severe cases compared to those in mild/moderate cases, demonstrating a higher inflammatory state during severe infection." (PMID 33937149, 2021). "C-reactive protein (CRP) is widely used as a routine clinical marker of inflammation, infection and tissue damage." (PMID 34257595, 2021). "Currently used biological markers (biomarkers) such as C-reactive protein (CRP) and procalcitonin (PCT) lack discriminatory power to diagnose infection in older patients (> 65 years)." (PMID 34649512, 2021). "During infection and trauma, the secretion of pro-inflammatory cytokines including IL-1, IL-6, and TNF-α, induce the production of C-reactive protein (CRP), procalcitonin (PCT), ferritin, and serum amyloid A (SAA) as common inflammatory mediators." (PMID 35126355, 2021). "With K96243 infection, levels of AST, ALP, LDH, BUN, and CRP levels trended insignificantly higher at both time points." (PMID 33571211, 2021).
infection (continued). "C-reactive protein level (CRP), white blood cell count (WBC), temperature and confirmed systemic clinical infection were used as systemic markers of inflammation." (PMID 34563211, 2021). "Serum CRP and synovial fluid percentage of polymorphonuclear neutrophils (PMN%) were significantly higher in the infection group than in the aseptic group." (PMID 34372816, 2021). "Most patients had increased levels of white blood cell counts (WBC), neutrophil percentage (NE%), C-reactive protein (CRP), procalcitonin (PCT), and fibrinogen, which were considered to be the markers for infection." (PMID 34157983, 2021). "Diagnostic accuracy of Procalcitonin (PCT), C-reactive protein (CRP), and White Cell Count (WCC) to diagnose infection on ECMO." (PMID 35155322, 2021). "CRP and PCT have been widely used as early predictors of anastomotic leak and infection in colorectal surgery, gastrointestinal surgery, and pancreatic surgery." (PMID 33784995, 2021). "By contrast, this present study also included clinical outcomes of infection, the need for therapeutic procedures, ICU admission, and scoring systems of Ranson score, Marshall score, EPIC score, and CRP levels for investigating." (PMID 34727802, 2021). "In distinguishing between microbiologically confirmed bacterial (n = 193) and viral (n = 291) infections, the FCBI-index method was superior to serum C-reactive protein (CRP) and procalcitonin (PCT)." (PMID 34844193, 2021). "PSP performed slightly better than CRP and PCT for detecting infection among adult hospitalized patients (p = 0.044 and p = 0.010, DeLong test)." (PMID 34049579, 2021). "With the continuous treatment with teicoplanin and imipenem for 15 days, the infection symptom was improved with a normal body temperature of 36.6 °C, a PCT level of 0.7 ng/ml and a CRP level of 76.8 mg/L." (PMID 34120601, 2021). "C-reactive protein (CRP) is an acute-phase protein produced by liver cells in response to injury, infection or inflammation." (PMID 34575258, 2021). "Several components are produced from hepatic cells infected with the dengue virus, such as CRP, SAP and ferritin in the early stage of infection." (PMID 33436908, 2021). "With that being said, we argue that CRP value at a given time point is too sensitive to any stress, including persistent PJI, minor infection in another organ, or discomfort from the joint." (PMID 34856956, 2021). "We found that CRP, complement complex C5b-9, and LDH were still higher in PC patients, despite the infection being abolished and despite the severity of the pathology." (PMID 34944747, 2021). "Despite a similar prevalence of individual infections, WBC total count, and differential and CRP concentrations, some cytokines differed across SFH classifications." (PMID 33898918, 2021). "Although there are some studies on above indicators as infection markers, the comparative analysis of PCT, CRP and WBC among patients with bacterial, viral and mycoplasmal ARTI is rare." (PMID 34836530, 2021). "Several studies have shown that the NLR has greater prognostic power than traditional markers for infection such as WBC count, neutrophil count, and CRP in adult CAP patients." (PMID 33857241, 2021). "CRP and SAA levels increased rapidly during the early period of 2019-nCoV infection; moreover, indices of severe cases increased to higher levels than those with mild disease." (PMID 33627079, 2021). "Patients’ risk factors associated with periprosthetic joint infections (PJIs) include surgical site infection score (SSI), Charlson comorbidity index (CCI), BMI, serum C-reactive protein (CRP) levels, older age and sex." (PMID 34768700, 2021). "Traditionally, diagnosis of infection after joint arthroplasty includes measuring serum levels of ESR and CRP, however, in the acute phase they can be influenced by the surgical intervention." (PMID 34030692, 2021). "There were significant differences in the PCT, CRP, LA, LDH, and AST between infection and non-infection group (all P < .05)." (PMID 35049198, 2021).
infection (continued). "Regarding infection, he took WBC and CRP into consideration; however, we evaluated sludge and cervical elastase." (PMID 34987587, 2021). "Furthermore, included infants—both in the intervention arm and control arm—who may be sick and need hospitalization for any illnesses will receive standard care treatment at HLH, including study-funded optimal assessment of a potential infection with blood culture and CRP analyses (ancillary care)." (PMID 33926519, 2021). "The virus-induced infection elicits inflammatory manifestations (absolute lymphocyte count and levels of LDG, CRP, ferritin, D-dimer, and IL-6) that correlate with a CS scenario (lymphocytopenia, hypercytokinemia, hyperinflammation)." (PMID 34858403, 2021). "C-reactive protein (CRP) is an acute-phase reactant, and its circulating concentration rises rapidly as a cytokine-mediated response to tissue injury, infection and inflammation." (PMID 33869637, 2021). "C reactive protein (CRP), an acute-phase reactant routinely tested on admission, reflects the innate immune response to infection." (PMID 34777361, 2021). "C-reactive protein (CRP) is a primary indicator of tissue damage, infection, and inflammation in common clinical trials." (PMID 34754275, 2021). "A meta-analysis showed that PSP performed better than C-reactive protein (CRP) and procalcitonin for detecting infection among hospitalized patients, and that the combination of PSP and CRP further enhanced its accuracy." (PMID 34325711, 2021). "Patients with microbiologically or clinically documented infection had significantly higher baseline levels of PCT and lower levels of CRP/PCT than subjects with TRF." (PMID 33777975, 2021). "Daily data on PCT, CRP and WCC were assessed in relation to microbiologically confirmed, and clinically suspected infection on ECMO using operating characteristics (ROC) curves." (PMID 35155322, 2021). "CRP, an acute-phase protein synthesized by the liver, and PCT, a marker for detecting infection/inflammation, have been receiving attention in predicting mortality of diseases, including AKI." (PMID 34141715, 2021). "C-reactive protein (CRP) is synthesized mainly in the liver and released into the bloodstream in response to an acute phase of tissue damage or infection." (PMID 34532198, 2021). "We applied a stepwise approach to evaluate the performance of PSP and compared it to those of CRP and PCT for detecting infection in adult hospitalized patients presenting to the ER or the ICU." (PMID 34049579, 2021). "Inflammatory markers, such as C-reactive protein (CRP), interleukin-6 (IL-6), and tumor necrosis factor-α (TNF- α) are shown to markedly increase in response to infection and tissue damage, as well as in active state of disease." (PMID 32731638, 2020). "In populations where inflammation or infection is widespread, ferritin should be measured concurrently with two acute phase response proteins such as AGP and CRP." (PMID 32635675, 2020). "The results of this study demonstrated differences between the concentrations of Hp, SAA, CRP, and AGP in milk derived from clinical infection by different pathogens." (PMID 32867136, 2020). "CRP and WBC are well-known surrogate markers of infection, and are activated by interleukin-6 or tumour necrosis factor-alpha produced by monocytes or macrophages." (PMID 32706758, 2020). "In the same study, 27.3% and 7.9% participants showed high levels of inflammatory markers; C reactive protein (CRP) and alpha A glycoprotein (AGP) suggestive of infection or other inflammatory processes." (PMID 33187486, 2020). "The levels of CRP, Fer, PCT, and IL-6, an acute phase protein, increase in the body immediately in response to infection or tissue damage." (PMID 33537326, 2020). "It is well-known that PCT, IL-6, CRP, and also IPF are strongly related with infections; hence, we also examined the results after excluding patients who developed an infection during the first 3 days after surgery." (PMID 37360622, 2020).
infection (continued). "In conclusion, our study is one of the first to systematically assess different APPs (⍺-2MG, SAA, CRP, and Hp) in TBL disease/infection." (PMID 32470023, 2020). "Among the most important APPs is C-reactive protein (CRP) that consequently is frequently used in diagnostics as a marker of inflammation and infection." (PMID 33519818, 2020). "In our study, the participants with CDI exhibited clear signs of infection, substantiated by the considerably increased values of WBC and CRP." (PMID 32796569, 2020). "NLCR had a worse ability to discriminate severe infection (AUROC 0.626; 95% CI 0.581–0.671) than conventional markers such as CRP (0.685, 95% CI 0.641–0.730) and PCT (0.661, 95% CI 0.615–0.707)." (PMID 32527243, 2020). "Concerning infection‐related parameters, over 50% patients had increased erythrocyte sedimentation rate (ESR) and C‐reactive protein (CRP)." (PMID 32397011, 2020). "The DNI, which is a calculated parameter that reflects the ratio of immature granulocytes over total neutrophil count in the peripheral blood, was previously reported to be more predictive of infection and prognosis than WBC counts and CRP." (PMID 33148349, 2020). "Some biomarkers can help to differentiate lupus activity from infection in SLE patients, such as CRP >6 mg/dL or procalcitonin >0.38 ng/mL." (PMID 33336061, 2020). "Previous studies have reported that HDF provided greater clearance of inflammatory cytokines compared to HD, and resulted in lower C-reactive protein (CRP) concentrations, although overall infection rates were comparable." (PMID 32012159, 2020). "In this study, we wanted to test the values of CRP, MRP8/14, and HNE in predicting KD over an infection." (PMID 32775314, 2020). "The prevalence of elevated CRP and AGP, biomarkers of inflammation and infection, were 15% and 33%, respectively." (PMID 32844187, 2020). "CRP measurement is simple, often automated, and inexpensive; thus, CRP is the most commonly measured APR for detecting infection." (PMID 33211747, 2020). "The significantly higher ultrasensitive CRP levels in CRC patients, compared to age-matched controls, illustrate the presence of active infection/inflammation in these patients." (PMID 32472080, 2020). "After adjusting the potential confounders, Hb, CRP, N%, and PLT were indications of iKD when compared with ADV infection (area under the curve [AUC]: 0.872, 0.939, 0.707, and 0.684, respectively)." (PMID 32923416, 2020). "Serum amylase and CRP levels in AT (n = 52) and PTA (n = 54) patients with different infection symptoms." (PMID 32243441, 2020). "Similar to infection detection for septic patients, the most commonly used laboratory parameters for the detection of an infection following LTX are C-reactive protein (CRP) and procalcitonin (PCT)." (PMID 33142943, 2020). "The only newborn with proven infection was born asymptomatic at 41 weeks' gestation with a positive PCT value (PCT level, 0.91 ng/l) and CRP level of 9.7 mg/L at 12 h after birth." (PMID 32363168, 2020). "Among the 20 patients with increased CRP levels and true positive 18F-FDG-PET/CT scans the final diagnosis was infection in 13 (65%), NIID in 4 (20%), and malignancy in 3 (15%)." (PMID 32635566, 2020). "In cases of systemic inflammation and infection, the traditional inflammatory mediators, such as white blood cell (WBC), C-reactive protein (CRP), and acute-phase proteins, are used for diagnosis and follow-up." (PMID 33083171, 2020). "Inflammation contributes to the elevation of the CA 19-9 value, and it can be assessed by monitoring the acute-phase proteins; one of these is the C-reactive protein (CRP), which rises in response to infection, injury and neoplasms." (PMID 32756322, 2020). "CRP and SAA are secreted mainly by hepatocytes produced in response to infection, trauma, and other inflammatory conditions." (PMID 32245401, 2020).